PIM1 (Pim-1 proto-oncogene, serine/threonine kinase)
Diseases named in the same sentence as PIM1 in open-access papers (continued):
Sharing a sentence is not in itself a finding about the gene and the disease.
lymphoma (continued). "Patients with lymphoma involvement in the GI tract had significantly decreased PIM1 (9.1 vs. 25.0%, P = 0.034) and MYD88 (0 vs. 20.8%, P = 0.001) mutations than those without GI tract involvement." (PMID 34557402, 2021). "For example, several of our top genes showed a tight SNV clustering pattern associated with elevated expression, including MYC, BCL2, PIM1 and IGLL5 in lymphoma." (PMID 33554123, 2021). "A large body of biological data suggests inhibition of Pim-1 as aninteresting point of intervention to treat certain human leukemiaand lymphomas." (PMID 31359998, 2019). "PIM1, identified as a preferential integration site for moloney murine leukemia virus to induce T-lymphomas in mice, belongs to a small group of kinases with two homologues (PIM2 and PIM3)." (PMID 29467592, 2018). "In several human cancer types, including T-and B-cell leukemia and lymphomas, the overexpression of PIM1 inhibits apoptosis, promotes proliferation, and prevents differentiation and maturation." (PMID 29467592, 2018). "Studies in others extra-nodal lymphomas, such as central nervous system and testis lymphomas, also showed MYD88, CD79B and PIM1 as the most frequently mutated genes, and points out a common molecular profile for extra-nodal DLBCL." (PMID 29262531, 2017). "Pim-1 transgenic mice carrying two copies of the transgene or a single copy of the transgene with optimized ribosomal-binding site succumbed to lymphomas before reaching reproductive age3." (PMID 29042609, 2017). "The importance of PIM1 in the development and evolution of hematologic malignancies, especially in lymphomas, has been known for many years." (PMID 29262531, 2017). "miR-33a also functions as a tumor suppressor miRNA through its capacity to downregulate the expression of oncogenic kinase Pim-1 in K562 lymphoma and colon carcinoma." (PMID 26622808, 2015). "The proviral insertion in murine (PIM) lymphoma proteins are a serine/threonine kinase family composed of three isoformes: Pim-1, Pim-2 and Pim-3." (PMID 25491234, 2014). "Pim-1 was identified in murine leukaemia virus (MuLV)-induced lymphomas that frequently contains proviral insertions which were associated with the transcriptional activation of the Pim-1 gene frequently associated with enhanced tumorigenesis." (PMID 25121590, 2014). "Eμ-N-myc;Eμ-pim1 bi-transgenic mice had severe anemia and lymphoma with involvement of all lymphoid organs, while a profound acceleration of lymphomagenesis was observed in Eμ-L-myc;Eμ-pim1 bi-transgenic mice." (PMID 24860787, 2014). "In 1984, Cuypers and co-workers identified pim1 by cloning the retroviral integration sites in Moloney-murine leukemia virus (M-MuLV)-induced lymphomas." (PMID 24860787, 2014). "The inoculation of newborn BALB/c or C57BL1O mice with M-MuLV revealed insertions near the c-myc, pim1, or pim2 genes in the primary lymphomas." (PMID 24860787, 2014). "Co-expression of both Eμ–Pim1 and Eμ–Myc was incompatible with life, leading the transgenic mice to succumb to lymphomas in utero or around birth." (PMID 25491234, 2014). "When the Eμ-pim1 transgene was simultaneously introduced to this mouse model, the incidence of spontaneously occurring lymphomas was significantly higher than in Eμ-pim1 single-transgenic mice of the same genetic background." (PMID 24860787, 2014). "MiR-33a decelerates cell proliferation acting through inhibition of proto-oncogene Pim-1 in lymphoma and colon cancer cells." (PMID 23527086, 2013). "This provided strong evidence for cooperation between pim-1 and myc family proto-oncogenes in development of T-lymphoma." (PMID 21994739, 2011). "Taken together, the data indicate that Pim-3 is the main Pim kinase overexpressed in Myc-induced lymphomas from mice and patients whereas Pim-1 and Pim-2 are more sporadically overexpressed." (PMID 21646687, 2011). "For instance, T-lymphomas induced by M-MuLV predominantly show activation of c-myc, pim-1 and/or pim-2." (PMID 21994739, 2011).
lymphoma (continued). "The oncogenic nature of Pim-1 and Pim-2 was confirmed by the observation that transgenic mice over expressing these kinases in the lymphoid system developed lymphomas." (PMID 22193779, 2011). "Over-expression of the Pim-1 gene in B and T cells in transgenic mice resulted in a high level of lymphoma development in these mice, confirming the oncogenic properties of this protein." (PMID 16403219, 2006). "PIM1 encodes a serine/threonine kinase that is known to be frequently mutated and overexpressed in DLBCL and plays an important protumorigenic role in this lymphoma." (PMID 41295250, 2025). "PIM1 was expressed in lymphoma cells in 27 (54%) of 50 cases." (PMID 38335426, 2024). "Besides its role in the pathogenesis of lymphoma, PIM1 expression is also elevated in other cancers." (PMID 34681783, 2021). "Initially, the gene encoding PIM1 (Proviral Integration site for Moloney Murine Leukemia Virus) was discovered in murine lymphoma samples and shown to be activatable by the integration of the murine leukemia virus into the 3′untranslated region of the PIM1 gene." (PMID 34681783, 2021). "Taken together that hepatitis seropositivity is associated with DLBCL, CLL and MZL risk and that AICDA promiscuous off-target activity, highly present in lymphomas and induced by viral infection, can provoke important alterations (example translocations of PD-L1/PD-L2 with PIM1, TP63, and IGH loci)." (PMID 33374413, 2020). "Based on the up-regulation of the proviral integration site of the Moloney murine leukemia virus (Pim) kinase family (Pim1, 2, and 3) observed in several types of leukemias and lymphomas, the development of pan-Pim inhibitors is an attractive therapeutic strategy." (PMID 31671637, 2019). "However, when Pim1 is co-expressed in mice with the oncogene c-Myc, 100% of the transgenic mice die of lymphomas in utero." (PMID 31671637, 2019). "The levels of PIM1 has been shown to be elevated in human myeloid and T-cell leukemias and lymphomas but alteration in PIM kinase expression has also been identified in prostate, liver, bladder, pancreatic, gastric, head & neck squamous cell carcinoma, oral, and colorectal in human patients." (PMID 25238262, 2014). "Eμ-Pim1 mice have a very low rate of developing T-cell lymphomas with a long latency, but infection with M-MuLV virus dramatically increases the incidence of lymphoma and shortens the latency of T-cell lymphoma development (56–64 versus 154 days)." (PMID 24860787, 2014). "Because the mortality in Pim1 mice associated with ENU exposure was closely related to the onset of neoplastic development, the Pim1 transgenic mouse models were considered optimal to test carcinogens and to assay agents for the chemoprevention of lymphomas." (PMID 24860787, 2014). "pim-1 is a weak oncogene that shows strong synergy with c-myc in lymphomas and prostate tumors." (PMID 24860787, 2014). "PIM1 is also known to be a target locus for aberrant somatic hypermutation in some lymphomas." (PMID 20515470, 2010). "Lymphoma risk was found to be significantly higher in the exposed Eμ-Pim1 mice than in the controls, mostly pronounced for non-lymphoblastic lymphoma." (PMID 15538947, 2004). "Therefore, Pim-1, along with other proto-oncogenes, may have a substantial role in the development of lymphomas and presents as an interesting therapeutic target." (PMID 36694243, 2023). "The pim-1 proto-oncogene was first identified as a locus frequently activated by proviral integration in Moloney murine leukemia virus induced mouse T-cell lymphomas and pim-2 was identified as a gene frequently activated in secondary transplants of virus induced lymphomas." (PMID 22193779, 2011). "Sequence studies of the entire exome and transcriptome of lymphoma tissues have identified MYD88 and PIM1 as involved in the development and oncogenic signaling." (PMID 38335426, 2024).
lymphoma (continued). "Previous studies have reported a high expression of PIM-1 and PIM-2 in ABC-DLBCL, which helps to distinguish it from germinal center B cell subtype lymphoma." (PMID 36871027, 2023). "Notable genes with SNV-associated increased expression include TERT, COPS3, POLE2 and HDAC2—involving multiple cancer types—MYC, BCL2, PIM1 and IGLL5—involving lymphomas—and CYHR1—involving pediatric low-grade gliomas." (PMID 33554123, 2021). "Since PIM1 has been shown to promote c-MYC-dependent transcriptional activity, we sought to identify possible PIM1 and c-MYC target genes in lymphoma cell lines." (PMID 26643319, 2015). "Similarly, proto-oncogene PIM1, a member of the PIM family of serine/threonine kinases, was identified from lymphoma samples as a frequently activated gene, which is highly conserved evolutionarily." (PMID 36968004, 2022). "The most frequently mutated genes (PIM1, MYD88, CD79B, and CARD11) are more prevalent in non-GCB DLBCL as has been addressed in previous publications in both extra-nodal and nodal lymphomas." (PMID 29262531, 2017). "Taken together, these observations provide a rational for targeting PIM1 and PIM2 in c-MYC expressing aggressive lymphomas including ABC-DLBCL and BL, in which PIM kinase inhibition might reduce c-MYC-mediated cell proliferation." (PMID 26643319, 2015). "The precise mechanism by which Pim-1 and 2 promote the formation of lymphomas is not fully understood, however it has been suggested that Pim-1 synergises with c-myc in this process." (PMID 16403219, 2006). "B[a]P, given three times a week by oral gavage for 13 weeks at 4.3, 13, or 39 mg/kg body weight resulted in a dose-dependent increase in lymphomas, with up to a 90% incidence in Eμ-Pim1 mice during the observation period of 40 weeks; in contrast, the non-transgenic mice did not develop lymphomas." (PMID 24860787, 2014).
breast carcinoma (42 papers, 2010 to 2026). "PIM1 gene is considered to be the causative genes for epithelial origin cancer line diseases such as prostate and breast cancer as well as hematological tumors such as diffuse large B-cell lymphoma, which is closely related to the risk of cancer occurrence." (PMID 35672846, 2022). "We next investigated the mechanism underlying Pim1 inhibitor-mediated anti-cancer activity in HER2-expressing breast cancer cells." (PMID 34267653, 2021). "PIM1 belongs to the serine/threonine kinase family and its overexpression has previously been implicated in diseases such as ovarian cancer and breast cancer." (PMID 33933144, 2021). "Taken together, these results suggest that EGFR and HER2 expressions are strongly associated with Pim1 expression and the sensitivity to Pim1 inhibitors in breast cancer cells." (PMID 34267653, 2021). "Overexpression of Pim1 has been observed in many cancer types and is associated with the poor prognosis of breast cancer." (PMID 34267653, 2021). "In line with this notion, we found that PML is associated to the promoter regions of MYC and PIM1, consistent with their direct correlation in breast cancer specimens." (PMID 31570853, 2020). "To address whether Pim1 regulates HER family expression in breast cancer, we first examined the association between Pim1 and HER family protein expressions using a panel of breast cancer cell lines by western blot." (PMID 34267653, 2021). "With this data in mind, we first evaluated the association of PML, MYC, and PIM1 in breast cancer." (PMID 31570853, 2020). "It has been shown that estradiol-induced PIM-1 overexpression in breast cancer leads to the phosphorylation of key proteins, which in turn suppresses the expression of cell cycle inhibitors (CDKN1A and CDKN2B)." (PMID 40565356, 2025). "Upregulation of PIM-1 mRNA and protein expression has been also observed in human breast cancer cells compared to normal breast tissue." (PMID 40565356, 2025). "PIM-1 has demonstrated higher expression levels in various solid cancers, including prostate, colon, hepatic, pancreatic, and breast cancers, as well as hematological cancers like leukemia, multiple myeloma, and diffuse large B cell lymphomas (DLBCL)." (PMID 39521748, 2025). "As PIM1-3 kinases are implicated in breast cancer progression, we examined the combined effect of UM171 and PAN-PIM inhibitor LGH447 on proliferation of MDA-MB-231 cells." (PMID 38874684, 2024). "Recent studies indicate that targeting PIM1 significantly suppresses breast cancer metastasis as well as the PIM1/STAT3 axis." (PMID 36982538, 2023). "Increased expression of miR-486-5p significantly decreased breast cancer cell proliferation and induced a G1 arrest, acting on its direct target the oncogene PIM-1." (PMID 36936170, 2023). "First, we determined the sensitivity of various breast cancer cell lines to these Pim1 inhibitors in MTT assays and analyzed the correlation of Pim1 protein expression with the IC50 of these two inhibitors." (PMID 34267653, 2021). "Other molecules regulate STAT3-modulated breast cancer metastasis, such as proto-oncogene serine/threonine-protein kinase (PIM1), miRNA, Mucin-1-C (MUC1-C), natriuretic peptide receptor A (NPRA), and RhoU." (PMID 34488773, 2021). "Surprisingly, when analyzing the prognostic role of PIM1 by Kaplan–Meier analysis, we observed that in breast cancer cases in general, PIM1 mRNA upregulation is rather protective." (PMID 33775697, 2021). "PIM1 promotes cell invasion, epithelial to mesenchymal transition process, and cancer cell stemness in IL-6-treated breast cancer cells." (PMID 34519263, 2021). "More importantly, Pim1 inhibitor overcame the resistance of breast cancer cells to HER2 tyrosine kinase inhibitor lapatinib." (PMID 34267653, 2021). "PIM1 knockdown reduced BCL2 expression, and dynamic BH3 profiling analysis revealed that PIM1 prevents mitochondrial-mediated apoptosis in breast cancer cells." (PMID 34503111, 2021).
breast carcinoma (continued). "miR-486-5p has been detected in various cancer cells, and its overexpression inhibits cell proliferation in leukemia cells, through targeting forkhead box protein O1 (FOXO1), and accelerates anti-proliferative effects via PIM-1 in breast cancer cells." (PMID 34830336, 2021). "In this study, we found that Pim1 expression was strongly associated with HER2 expression and that HER2-overexpressing breast cancer cells were more sensitive to Pim1 inhibitor-induced inhibitions of cell viability and metastatic ability." (PMID 34267653, 2021). "Here, in our study, we revealed that PIM1, an oncogenic serine‐threonine kinase and a well‐proven contributor to the tumorigenesis of breast cancer, was involved in BrCSCs regulation and promised to be a new target for eradicating BrCSCs." (PMID 32307917, 2020). "PIM1 is aberrantly expressed in several cancers, and its pharmacological inhibition in breast cancer, T-ALL cell lines, adult T-cell leukemia, and T-cell lymphoma (ATL) is therapeutically effective." (PMID 33488754, 2020). "Here, in our work, we extended our knowledge of PIM1 as an oncogene, by revealing the possible role of PIM1 in regulating the BrCSC‐like traits of breast cancer cells." (PMID 32307917, 2020). "As to our knowledge, this is the first comprehensive research of PIM1 expression across breast cancer tissues with different hormone receptors status." (PMID 32307917, 2020). "To elucidate the contribution of PIM1 to BrCSCs, we used clonogenic assay to evaluate the impact of PIM1 inhibition on the ability of breast cancer cells to form colonies." (PMID 32307917, 2020). "As PIM1 was significantly upregulated by IL-6/STAT3 activation, we further investigated the roles of PIM1 in IL-6-induced breast cancer cell EMT and stemness." (PMID 30989585, 2019). "Functional analysis using ectopic overexpression and RNAi knockdown implied that PIM1 promoted breast cancer cell malignancy phenotypes." (PMID 30989585, 2019). "Previous study indicated that PIM1 located on chromosome 6p21-p25, a recurrent amplicon, and the copy number amplification was responsible for the upregulation of PIM1 in breast cancer." (PMID 30989585, 2019). "Transwell assay was used to detect the invading ability of breast cancer cells induced by IL-6 or PIM1." (PMID 30989585, 2019). "Previous report indicated that PIM1 was regulated by estrogen signaling and contributed to the growth of breast cancer cells." (PMID 30989585, 2019). "Taken together, these results indicated that c-myc was involved in PIM1-induced breast cancer cell EMT and stemness." (PMID 30989585, 2019). "In this study, PIM1 was shown to play a critical role in ccRCC progression, which is consistent with previous evidence showing that overexpression of PIM1 contributes to the progression of cancers, including breast cancer, mesothelioma and glioblastoma." (PMID 29472550, 2018). "It was found that miR-486-5p was repressed in breast cancer tissue and cell lines, where it was validated to target the oncogene PIM-1." (PMID 28030794, 2017). "It is possible that the reason that hGBP-1 functions one way in ovarian cancer and another in breast cancer is because it interacts with adifferent isoform of PIM1." (PMID 28090373, 2016). "Taken together, these data suggest that Pim1 counteracts the effects of Notch1 in regulation of breast cancer cell metabolism." (PMID 27281612, 2016). "In breast cancer, where the larger isoform is expressed, elevated PIM1 correlated with improved RFS." (PMID 28090373, 2016). "miR-486–5p was found to be downregulated in breast cancer patients with lymph node metastases and to exert its antiproliferative function and promote apoptosis by directly downregulating PIM-1 expression." (PMID 25793394, 2015). "Furthermore, PIM1 phosphorylated P-glycoprotein, shielding it from proteasomal degradation, which augmented its expression on the cell surface and contributed to breast cancer resistance to doxorubicin." (PMID 40992658, 2025).